AR (androgen receptor)
Diseases named in the same sentence as AR in open-access papers (continued):
Sharing a sentence is not in itself a finding about the gene and the disease.
prostate carcinoma (continued). "Finally, the treatment of prostate cancer cell lines with this cNDI in combination with the AR antagonist Enzalutamide (used in second line therapies) resulted in a synergistic interaction in AR-positive but not in AR-negative cell lines." (PMID 30682828, 2019). "Moreover, it has recently been shown that AR-null prostate cancers that do not undergo neuroendocrine differentiation, or ‘double negative’ metastatic prostate cancers have sustained FGF-MAPK signaling and that these cancers are sensitive to MEK and ERK1/2 inhibition in vitro and in vivo." (PMID 30314329, 2018). "In addition, KDM4B is not only required for enhancing androgen receptor (AR) transcriptional activity through histone modification, but it also enhances AR protein stability via inhibition of AR ubiquitination, demonstrating the functional connection between AR and KDM4B in prostate cancer." (PMID 29342868, 2018). "In addition to its roles in WNT and Notch signaling pathways regulating the progression of prostate cancer (most recently reviewed), calcium-calmodulin kinase (CAMK) II in prostate cancer cells was shown to mediate the activation of protein kinase AKT under the conditions of reduced AR expression." (PMID 29921791, 2018). "It is possible that the AR-negative prostate cancer cells grow out of this stem cell population during androgen deprivation therapy, which means that NF-κB inhibition could be a promising target to prevent the evolution of AR-negative prostate cancer cells." (PMID 30158439, 2018). "Taken together, our data indicate a novel, crucial role for AR in reducing TF expression, which could be important for increased TF expression and TF‐positive MV release in androgen‐deprived prostate cancer patients, and contribute to elevated VTE rates in prostate cancer patients." (PMID 29427323, 2018). "Proteomic analysis between prostate cancer cell line LNCaP (L+ns) and LNCaP lacking ID4 (L(−)ID4) revealed elevated levels of Hsp27 and FKBP52, suggesting a role for these AR‐associated co‐chaperones in promoting constitutively active AR signaling in L(−)ID4 cells." (PMID 28252832, 2017). "However, the molecular mechanisms of AR action in prostate cancer are not very clear." (PMID 28881808, 2017). "Interestingly, MT1-dependent mechanisms of melatonin action were defective in AR-null, but not AR-intact, prostate cancer cells, which may further imply a functional interplay between melatonin-MT1 axis and AR signaling." (PMID 28420185, 2017). "Interestingly, when characterising CTCs according to the presence of AR, we found that 100% of patients with AR-positive CTCs were EGFR-negative in the prostate cancer tissue, whereas up to 75% of patients with AR-negative CTCs presented EGFR-positive tissue (p= 0.5)." (PMID 29050295, 2017). "Therefore, the regulation of AR by ciglitazone (and possibly other TZDs) in AR-positive, castration-resistant prostate cancer cells may not prevent ciglitazone-induced reductions in cell proliferation." (PMID 29181019, 2017). "However, it remains unclear whether CCL2 promotes prostate cancer progression in prostate cancer cells regardless of therapeutic targeting of androgen/AR signaling." (PMID 26701731, 2016). "Therefore, neither PSA nor AR index level were reliable prognostic markers for prostate cancer." (PMID 27779102, 2016). "From these data, we concluded that an AR-GSR enriched in the sub-clonal architecture of tumour C-12A was responsible for expression of a tumour-specific set of AR-V species that could support constitutive, ligand-independent AR transcriptional activity and prostate cancer cell growth." (PMID 27897170, 2016).
prostate carcinoma (continued). "Although the effects of the AR on gene repression are largely unknown, a previous report suggested that the repressor element (RE)-1 silencing transcription factor (REST) mediates the effects of AR on suppression of brain-derived neurotrophic factor (BDNF) in prostate cancer cells." (PMID 27144435, 2016). "But in this study, we could investigate for the first time that AR remains in the cytoplasm when AR positive prostate cancer cells are cultured in scaffolds without RGD as well as in case of an insufficient pore network (total porosity under 10 %) and a too less stiffness of around 10 kPa." (PMID 27386348, 2016). "Interestingly, a subset of ERα-negative/AR-positive cancers, sub-classified as “molecular apocrine” for histological reasons, exhibited transcriptomic profiles that were similar to those stimulated by AR signaling in prostate cancer cells." (PMID 26554309, 2015). "Collectively, these observations provide evidence for the hypothesis that AR can be an oncogene in certain ERα-negative breast cancers by acting as a “surrogate” ERα or by recapitulating the oncogenic program that stimulates growth of prostate cancer cells." (PMID 26554309, 2015). "Furthermore, enhanced AR expression and/or copy number amplification by increased STAT5 activation may promote lipid and androgen biosynthesis, as well as dysregulated cell cycle and DNA synthesis in prostate cancer cells." (PMID 26318424, 2015). "Moreover, it was established that TXA2-mediated PRK1 signalling can both mimic and augment androgen-induced H3Thr11 phosphorylation and cell migration in prostate cancer, providing a previously unknown functional link between the TXA2- TPα/TPβ signalling axis and the AR." (PMID 26296974, 2015). "Moreover, inhibition by ATO was more pronounced in prostate cancer cells expressing androgen receptor than in prostate cancer cells depleted of androgen receptor, and inhibition of androgen receptor activity by ATO and by the androgen receptor antagonist, bicalutamide, was additive." (PMID 26352139, 2015). "Finally, there are novel therapeutic agents including the once-daily androgen receptor signaling inhibitor enzalutamide, previously called MDV3100, which significantly prolonged overall survival in a randomized phase III trial that involved 1,199 men with castration-resistant prostate cancer." (PMID 25595907, 2015). "Accumulating evidence shows that androgen receptor (AR) activation and signaling plays a key role in growth and progression in all stages of prostate cancer, even under low androgen levels or in the absence of androgen in the castration-resistant prostate cancer." (PMID 26622945, 2015). "The M12 prostate cancer cell line is an AR negative line, so the effect of ARfl could be excluded." (PMID 25481872, 2015). "Also, the impact of MCT2 inhibition in PCa cells is still unknown and links between SLC16A7/MCT2 and major prostate cancer drivers such as Androgen Receptor (AR) ETS-related genes (ERG) have not previously been studied." (PMID 26035357, 2015). "Nonetheless, this PET tracer was sufficient in detecting AR-dependent changes in PSA expression levels in mouse tumour lesions, as well as in distinguishing PCa cells within bone lesions - both of which may be useful in the staging and clinical evaluation of advanced prostate cancer." (PMID 26116115, 2014). "However, clinical evidence and basic research study support the hypothesis that alternative mechanisms may be related to highly aggressive, metastatic phenotype in AR-negative prostate cancer cells or cancer-stem cells." (PMID 24297527, 2014). "Furthermore, calpain 2 can also cleave AR to generate a truncated, functional AR without ligand-binding domain in androgen-sensitive prostate cancer cells, which enables cancer cell adaptation to androgen-independent growth and proliferation during androgen-deprivation treatment." (PMID 24297527, 2014).
prostate carcinoma (continued). "Our present data strongly support the concept that long-term androgen deprivation may push androgen-sensitive prostate cancer cells evolve into AR-negative, more aggressive, androgen-independent disease state, with overexpression of calpain 2 enhancing its activity." (PMID 24297527, 2014). "Since experiments for elucidating the involvement of Cdk1 and Cdk2 in promoting NED were performed only in AR-positive prostate cancer cell lines, investigating the AR-negative cell lines might shed more light in proposed role of Cdk1 and Cdk2 deregulation in promoting NED." (PMID 24884804, 2014). "In agreement with our finding that the SPOP-binding motif 645ASSTT649 is located in the hinge domain of the AR, we demonstrated that none of the hinge domain null AR variants could be bound by SPOP, thereby escaping SPOP-mediated protein degradation in prostate cancer cells." (PMID 24508459, 2014). "A rapid decrease in the PSA level after PADT may be due to ablation of the androgen receptor function, and quick suppression of androgen/androgen receptor during PADT may have a negative effect on disease progression, because the androgen receptor can act as a tumor suppressor for prostate cancer." (PMID 24773608, 2014). "Beside its predictive value, AR in the absence of ER expression in TNBCs may have the potential for targeted therapy using pharmacological antagonists developed for the treatment of prostate cancer." (PMID 25510351, 2014). "Our identification of an ERα-NEAT1 axis illustrates a mechanism whereby prostate cancer cells may develop therapeutic resistance through positive selection of an alternate nuclear receptor signalling pathway in the absence of AR or during androgen ablation therapy." (PMID 25415230, 2014). "The same group demonstrated that overexpression of non-receptor tyrosine kinase Etk/BMX induced AR phosphorylation and castration resistance, suggesting that Etk/BMX is another tyrosine kinase of AR associated with castration-resistant progression of prostate cancer." (PMID 23896594, 2013). "This is supported by evidence that AR expression is preserved in most prostate cancer specimens, regardless of the stage and grade, and by the fact that only a small proportion of CRCP patients experience loss of AR expression, presumably through AR promoter methylation." (PMID 23667504, 2013). "A recent report has shown that the oncogenic function of EZH2 in cells of CR prostate cancer is independent of its role as a transcriptional repressor and involves its the ability to act as a coactivator for critical transcription factors including the androgen receptor." (PMID 24353195, 2013). "Then, in order to meet the need for clinically relevant models of prostate cancer-associated bone lesions, more recent hormone-independent models have been developed like MDA PCa 118 and Ace-1 that similarly to the PC3c model do not express AR and induce mixed lesions." (PMID 24069383, 2013). "In addition, microinjection of AR-specific antibody into the nucleus or treatment of cells with AR mRNA hammerhead ribozyme inhibits the proliferation of AR-positive, but not AR-negative, prostate cancer cells, indicating a critical role of AR in proliferation of AR-expressing prostate cancer cells." (PMID 23437213, 2013). "Therefore, Snail knockdown may alleviate maspin inhibition in AR-negative and –positive prostate cancer cell lines." (PMID 22857708, 2012). "Consequently, the AR may serve not only as a therapeutic target, but also as a candidate for biomarker panels predicting prostate cancer metastasis, independent of androgens." (PMID 22641253, 2012). "Importantly, as shown in prostate cancer, a combination of EGF and androgen further induced AR transcriptional activity in all the three bladder cancer lines tested and the AR antagonist HF completely abolished AR transactivation induced by EGF, androgen, or both at least in UMUC3." (PMID 22922989, 2012).
prostate carcinoma (continued). "As BFA appears to profoundly down-regulate AR expression, it was of interest to examine whether BFA might also affect other androgen-mediated cellular events (via AR) such as secretion of PSA, which is a useful biomarker for prostate cancer and under the androgenic control." (PMID 20102617, 2010). "These castrate-resistant prostate cancer cell lines do not undergo apoptosis when androgens are depleted or androgens antagonists are used; however, they stop proliferating and activate cell death if the AR protein level is reduced below a critical level both in vitro and in vivo." (PMID 20628607, 2010). "However, this does not exclude the other effects of RSV on AR and prostate cancer development." (PMID 19816598, 2009). "The results showed a significant negative correlation between AR activity in the epithelial compartment and the level of immune cell infiltration in the TME of human prostate cancer." (PMID 41486951, 2026). "PC3 cells do not express AR and PSA and are used as a model of prostate cancer resistant to androgen-deprivation therapy." (PMID 40806710, 2025). "Nonsurgical treatment of prostate cancer is typically ADT, which includes the use of AR inhibitors (e.g., bicalutamide, apalutamide) and androgen synthesis inhibitors (e.g., abiraterone)." (PMID 41281744, 2025). "In prostate cancer cell lines, Ar expression is promoted by GATA2 while GATA2 expression is repressed by androgen-AR action, forming a negative feedback regulatory loop." (PMID 40196482, 2025). "Furthermore, considering prostate cancer cells with neuroendocrine features, AR-negative phenotypes are cumulatively found in 36% of patients and 31% of metastatic tumors, a strong indication of the importance of cancer cells lacking the AR in advanced disease stages." (PMID 39858071, 2025). "PELP1 facilitates E2-induced AR signaling by forming a protein complex with AR and ESR2 on the DNA, leading to the proliferation of prostate cancer (PCa) cells in the absence of androgen, allowing for crosstalk between these steroid receptors." (PMID 41463382, 2025). "In this study, androgen receptor-negative PC-3 and DU145 cell lines were used among various prostate cancer cell lines." (PMID 40566490, 2025). "In advanced prostate cancer, strong CK8 expression with weak or absent CK5/6 expression is typically observed, whereas AR—a hormone receptor—remains highly expressed and is characteristic of prostatic adenocarcinomas." (PMID 41463218, 2025). "These prostate tumors, which can be classified as AR-negative, androgen-independent (ARneg-AI) cancer, are a subtype of CRPC that have more aggressive characteristics than ARpos-AI prostate cancer and are modeled by established cell lines PC3 and DU145." (PMID 39000112, 2024). "In prostate cancer, analyzed via electrophoretic mobility shift assay and pulldown assay, YBX1 can bind to 5mC-modified androgen receptor (AR) mRNA but not the unmodified one." (PMID 38255791, 2024). "Although another member of the GATA family, GATA2, regulates AR signaling in prostate cancer cells, proteomic studies have not identified GATA2 as being part of the AR interactome in prostate cancer cell lines or primary tissues." (PMID 38317241, 2024). "Therefore, we generated prostate cancer murine xenograft models with an intact human immune system (huNOG and huNOG-EXL mice) to test whether humanizing tumor-immune interactions would improve modeling of metastatic prostate cancer and the impact of androgen receptor-targeted and immunotherapies." (PMID 38820127, 2024). "However, it is currently difficult to conduct such clinical research as strong treatment centered on agents targeting the AR axis is being performed for metastatic castration-sensitive prostate cancer, so there may be no other way to speculate from the results of the DELC study." (PMID 38305451, 2024).
prostate carcinoma (continued). "Resistance to different stages of androgen blockers leads to increased malignancy and heterogeneity of prostate cancer, such as the trans-differentiation of classical prostate carcinoma to neuroendocrine prostate cancer (NEPC) and AR-negative prostate cancer." (PMID 38341429, 2024). "ROR-α and ROR-β expression do not noticeably change in prostate cancer, while ROR-γ expression is closely related to tumor development and is the key determinant of AR gene expression." (PMID 39011396, 2024). "For instance, prostate cancer frequently exhibits disruption of the PI3K/Akt/mTOR pathway, which is independent of androgen receptor (AR) signaling and promotes cell survival and proliferation." (PMID 39199550, 2024). "As prostate cancer progresses into the lethal CRPC stage, androgen becomes non-essential for the activation of AR due to several mechanisms, including the expression of constitutively active splice variants of AR." (PMID 38410785, 2024). "When prostate cancer is subjected to ADT, AR– cell populations and PCSCs are not completely eradicated, and instead undergo some genetic alterations to possess stemness properties of CRPC." (PMID 36969009, 2023). "Prostate cancer cells PC3, which lack endogenous AR, were transfected with AR-Flag together with Sema4D-Fc or vector-Fc, with or without WT or non-functional mutant forms of Ran—RanQ69L or T24N." (PMID 37563360, 2023). "Due to the vast implication of androgen receptor antagonists for castration-resistant prostate cancers (CRPC), neuroendocrinal progression of prostate cancer (NEPC) emerged as the worst stage of prostate cancer without means to cure." (PMID 36776320, 2023). "CRPC consists of multiple molecular and histologic subtypes of prostate cancer including neuroendocrine prostate cancer (NEPC) which takes on characteristics of neuroendocrine (NE) differentiation and is no longer responsive to AR-directed treatments." (PMID 37823778, 2023). "Even in prostate cancer cases lacking HRR alterations, the combination therapy of PARP inhibitors with androgen receptor inhibitors (ARi) holds great promise due to the synergistic treatment effects observed." (PMID 38138301, 2023). "PARP7 expression in primary prostate cancer tumors is correlated with both AHR and AR, which is not surprising given the TIPARP gene is a direct target of both transcription factors." (PMID 37077937, 2023). "In the AR‐negative cell line DU‐145 and PC3, the Au‐AR pep‐PROTAC drug showed no toxicity on AR negative prostate cancer cells under 1 μM." (PMID 35971165, 2022). "Both DHT and enzalutamide had the anticipated impact on canonical AR genes (FKBP5 and NDRG1) in an androgen-sensitive prostate cancer cell line and in differentiated hBECs (Donor B1)." (PMID 35110354, 2022). "c-FLIP is not the only AR target gene of importance in prostate cancer, and it will be interesting to evaluate the global impact of RON on AR targets and signaling." (PMID 35454943, 2022). "Therefore, although not a common mutation found in prostate cancer, its role in CRC could be highly significant especially as it is recognised that β-catenin has the ability to modulate the effects of AR by binding to the NTD, mutations in this region could therefore interfere with this process." (PMID 35173303, 2022). "Here we determined the impact of darolutamide, an AR antagonist with significant clinical efficacy in non-metastatic CRPC and metastatic hormone-sensitive prostate cancer on the prostate cancer proteome." (PMID 36611998, 2022). "Although some articles reported that ELK1 regulated AR transcription and thus affected the progression of AR-positive prostate cancer cells 29, the role of ELK1 in AR-negative prostate cancer have not been fully elucidated." (PMID 36439881, 2022). "Metformin inhibits migration and invasion of prostate cancer cells, independent of AMPK, with a more pronounced effect in AR-positive than in AR-negative cells." (PMID 35327549, 2022).